SOCS3 (suppressor of cytokine signaling 3)
Diseases named in the same sentence as SOCS3 in open-access papers (continued):
Sharing a sentence is not in itself a finding about the gene and the disease.
cytomegalovirus infection (2 papers, 2017 to 2023). A herpesvirus infection caused by Cytomegalovirus. "To assess the contribution of HCMV-induced SOCS3 upregulation to the neuropathogenesis caused by congenital HCMV infection, we first examined the impact of high SOCS3 expression on the biology of NPCs." (PMID 36753521, 2023). "Unlike the observations in wild-type HCMV infection (V), the mRNA and protein levels of SOCS3 remained unperturbed during UV-HCMV infection, indicating newly synthesized viral products are required for SOCS3 regulation." (PMID 36753521, 2023). "Different from the typical SOCS3 expression kinetics induced by those viruses, we reveal a biphasic regulation of SOCS3 expression by HCMV infection in NPCs." (PMID 36753521, 2023). "Taken together, these data demonstrate that pUL97 is the viral protein responsible for the sustained upregulation of SOCS3 during HCMV infection in NPCs." (PMID 36753521, 2023). "Our work reveals a new regulatory mechanism for SOCS3 expression in NPCs and provides insights into the neuropathogenesis induced by congenital HCMV infection." (PMID 36753521, 2023). "To determine how SOCS3 expression is regulated by HCMV infection, we first examined whether SOCS3 upregulation requires newly synthesized proteins." (PMID 36753521, 2023). "SOCS3 overexpression alone could reduce the expression of all these markers compared with the control group, which is interestingly similar to HCMV infection." (PMID 36753521, 2023). "Given SOCS3’s multiple roles in regulating infection and neural development, we wondered whether HCMV infection in the neural system affects SOCS3 expression and how the altered SOCS3 level contributes to the HCMV-induced brain maldevelopment." (PMID 36753521, 2023). "However, SOCS3 in the cytoplasm was gradually increased by HCMV infection, and the viral IE1 protein was restricted to the nucleus as usual." (PMID 36753521, 2023). "To study the role of SOCS3 in neuropathology caused by congenital CMV infection, we first sought to confirm whether CMV infection upregulates SOCS3 expression in vivo." (PMID 36753521, 2023). "In addition, we inspected the impact of HCMV infection on SOCS3 cellular distribution." (PMID 36753521, 2023). "In the scr control group, HCMV infection greatly boosted RFX7 and SOCS3 expression in NPCs compared with the mock-infected cells." (PMID 36753521, 2023). "Here we show that suppressor of cytokine signaling 3 (SOCS3), a negative feedback regulator of the IL-6 cytokine family signaling, was upregulated during HCMV infection in primary neural progenitor cells (NPCs) with a biphasic expression pattern." (PMID 36753521, 2023). "In summary, this study provides a mechanism for pUL97-mediated SOCS3 upregulation induced by HCMV infection in NPCs and reveals the negative impacts of sustained SOCS3 expression on neurogenesis." (PMID 36753521, 2023). "Consistent with the results in non-transduced NPCs, SOCS3 was upregulated during HCMV infection in scr-transduced NPCs." (PMID 36753521, 2023). "Here, we show that HCMV infection in NPCs upregulates SOCS3, a negative feedback regulator of IL-6 cytokine family signaling." (PMID 36753521, 2023).
dementia (2 papers, 2013 to 2023). Loss of intellectual abilities interfering with an individual's social and occupational functions. "FADD was reportedly involved in brain dopamine signaling, while SOCS3 can promote progression toward human immunodeficiency virus (HIV)-associated dementia in patients with HIV." (PMID 23936146, 2013). "It has been found that SOCS3 expression is significantly higher in the brains of AD patients compared to individuals with mild cognitive impairment or non-dementia individuals." (PMID 37916989, 2023).
diabetic cardiomyopathy (2 papers, 2021 to 2025). Diabetic cardiomyopathy is a disorder of the heart muscle in people with diabetes. "In diabetic cardiomyopathy, DNMT1-mediated methylation of the suppressor of cytokine signaling 3 (SOCS3) promoter suppresses its expression, promoting STAT3 activation and fibrotic remodeling." (PMID 40384946, 2025).
Diabetic Nephropathy (2 papers, 2020 to 2024). "This signaling pathway has an important role in diabetic nephropathy via an Angiotensin II- dependent mechanism, and is negatively regulated by Suppressor of Cytokine Signaling 3 (SOCS3) by either inhibiting the JAK tyrosine kinase activity or by competing with STATs on cytokine receptors." (PMID 33585587, 2020).
Down syndrome (2 papers, 2017 to 2025). "The biomarkers most frequently analyzed in studies of Down syndrome were IL-10, TNF-alpha, IL-1 beta, IL-4, IFN-gamma, and the genes STAT1, STAT3, and SOCS3, all of which are involved in the regulation of the immune response and periodontal inflammation." (PMID 41462866, 2025).
esophageal squamous cell carcinoma (2 papers, 2022 to 2025). Esophageal squamous cell carcinoma (ESCC) is a type of esophageal carcinoma (EC) that can affect any part of the esophagus, but is usually located in the upper or middle third. "In mouse esophageal squamous cell carcinoma, CAFs-secreted Wnt family member (WNT2) has been linked to suppression of the DC-initiated antitumor T-cell response via the suppressor of cytokine signaling 3 (SOCS3)/phosphorylated Janus kinase 2 (p-JAK2)/phosphorylated STAT3 (p-STAT3) signaling pathway." (PMID 36338519, 2022). "In esophageal squamous cell carcinoma (ESCC), CAF‐derived WNT2 inhibits DC differentiation through the SOCS3/p‐JAK2/p‐STAT3 signaling cascade, thereby suppressing immune responses." (PMID 41164803, 2025). "In esophageal squamous cell carcinoma, CAFs secrete WNT2 to inhibit the SOCS3/p‐JAK2/p‐STAT3 pathway, thereby suppressing CD8+ T‐cell activation." (PMID 41164803, 2025).
food allergies (2 papers, 2019 to 2025). "Ovalbumin (OVA)-induced food allergy can increase the phosphorylation of STAT3 and activate SOCS3." (PMID 40005151, 2025).
fungal infection (2 papers, 2015 to 2021). "The analysis of the M1/M2 (NOS2/ARG1 and SOCS3/SOCS1) ratios expressed by A/J and B10.A cells demonstrates that curdlan increases but laminarin decreases the M1/M2 ratios of A/J macrophages induced by fungal infection." (PMID 26388856, 2015). "Overall, a unifying role of SOCS3 is macrophage polarization across species has not been established, and further research are need to better define the role and mechanism of SOCS3 in the regulation of macrophage polarization against fungal infections." (PMID 34339354, 2021).
gastritis (2 papers, 2020 to 2022). Inflammation of the stomach. "In addition, SOCS3 is considered an important mediator of gastrointestinal inflammation, and the knocking out of SOCS3 in gastric epithelial cells can promote the occurrence of gastritis." (PMID 35444649, 2022). "We show that H. pylori positive gastritis patients express significantly higher SOCS3, but not SOCS1 and SOCS2, levels compared to H. pylori negative patients." (PMID 33023610, 2020).
helminth infection (2 papers, 2008 to 2017). "In rural Ghana, helminth infection is associated with low TLR2 as well as low SOCS-3 expression, whereas the expression of TLR2 is high in a European rural area." (PMID 18414649, 2008). "We sought to determine whether epithelial SOCS3, known to limit epithelial proliferation in intestinal injury and tumour models, impacts on susceptibility to helminth infection through influencing IEC turnover." (PMID 28508554, 2017). "However, although helminth infections are clearly associated with Th2 responses, we have found that SOCS-3 expression is decreased in helminth-infected children." (PMID 18414649, 2008). "So although both allergic disorders and helminth infections are characterized by Th2 responses, SOCS-3 is associated with allergic disorders, but not with helminth infection." (PMID 18414649, 2008). "In summary, ex vivo whole blood analysis of mRNA profiles in children infected with helminths compared to non-infected children living in a rural area in Ghana have shown that chronic helminth infections are associated with a lower expression of TLR2 and SOCS-3." (PMID 18414649, 2008). "We propose that SOCS3, as a natural endogenous regulator of IEC turnover, balances the magnitude and/or duration of inflammatory signaling maintaining IEC homeostasis and therefore modulates resistance to helminth infection." (PMID 28508554, 2017).
hepatitis C (2 papers, 2017 to 2022). "A significant relationship was recognized between SOCS3 basal expression levels and hepatitis C. In particular, the SOCS3 rs4969170 AA genotype has been strongly associated with failure of antiviral therapy." (PMID 36169255, 2022). "In studies on hepatitis C, the rs4969170AA genotype was associated with antiviral IFN-α resistance with increased SOCS3 expression in HCV patients." (PMID 28179578, 2017).
Hypoglycemia (2 papers, 2012 to 2022). A decreased concentration of glucose in the blood. "The Zip14 KO mice exhibited decreased circulating IL-6 with increased hepatic SOCS-3 following LPS, suggesting SOCS-3 inhibited insulin signaling which produced the hypoglycemia in this genotype." (PMID 23110240, 2012). "Interestingly, SOCS3 ablation in steroidogenic factor-1 (SF1)-expressing cells, which includes the ventromedial nucleus of the hypothalamus (VMH), reduces blood glucose levels in fed and fasted mice, even though the animals do not develop hypoglycemia." (PMID 35742928, 2022).
hypothyroidism (2 papers, 2014 to 2023). Abnormally low levels of thyroid hormone. "However, Socs3 gene expression was significantly upregulated by hypothyroidism itself and hypothyroidism plus castration in male rats (data not shown)." (PMID 38144555, 2023). "The level of SOCS3 mRNA was induced by hypothyroidism itself, whereas neither hypothyroidism nor hormonal replacement altered SOCS5." (PMID 24816529, 2014).
Infertility (2 papers, 2019 to 2021). "Furthermore, while HCD-fed male mice remained completely fertile, the female control mice developed HCD-induced infertility and this was prevented for over a month by SOCS3 knockout." (PMID 34502119, 2021).
inflammatory skin disease (2 papers, 2012 to 2024). Inflammatory skin disorders covers a broad category that includes many conditions ranging in severity, from mild itching to grave medical health complications These disorders are common in people of all ages and races. "The present study proposed that negative regulator for cytokine signaling SOCS3 plays a crucial role to maintain the keratinocyte homeostasis, and showed that defective SOCS3 expression causes inflammatory skin disease." (PMID 22792286, 2012). "SOCS1 and SOCS3 are the most well-characterized SOCS members in skin inflammatory diseases, where their inhibitory activity on cytokine activated JAKs and consequent anti-inflammatory action has been widely investigated in epidermal keratinocytes." (PMID 38975347, 2024).
insulinoma (2 papers, 2010 to 2015). "A similar result was obtained in the hamster insulinoma cell line HIT-T15, although LEPRb-FYY and LEPRb-FFY differed in their sensitivity to SOCS3 only at higher expression levels." (PMID 20059770, 2010).
lentivirus infection (2 papers, 2018 to 2023). Virus diseases caused by the Lentivirus genus. "After lentivirus infection, SOCS3 was significantly overexpressed." (PMID 30369485, 2018).
liver cirrhosis (2 papers, 2020 to 2021). "Suppressor of cytokine Signaling 3 (SOCS-3) proteins can cause the dysfunction of IL-22-mediated hepatocyte regeneration, and HCV core protein and SOCS-3 are highly expressed in patients with liver cirrhosis and HCC." (PMID 34434945, 2021).
mantle cell lymphoma (2 papers, 2021 to 2025). Mantle cell lymphoma is a rare form of malignant non-Hodgkin lymphoma affecting B lymphocytes in the lymph nodes in a region called the ``mantle zone''. "Decreased SOCS3 expression due to methylation was detected in a considerable proportion of mantle cell lymphoma (MCL) patients, with a trend for worse outcomes in this cohort." (PMID 34604264, 2021). "SOCS3 was shown to promote apoptosis and downregulate NF-κB activity when SOCS3 was reconstituted in SOCS3-negative mantle cell lymphoma." (PMID 40670673, 2025).
mesothelioma (2 papers, 2022 to 2024). A usually malignant and aggressive neoplasm of the mesothelium which is often associated with exposure to asbestos. "To validate our whole-genome screens, we used CRISPR/Cas9 mutagenesis with two independent sgRNAs to mutate NF1, SOCS3, and VGLL4 in H226 and H2052 cells, as well as a third mesothelioma cell line, MSTO-211H, which harbors inactivating mutations in both LATS1 and LATS2." (PMID 39103676, 2024).
metastasis (2 papers, 2022 to 2023). The spread or migration of cancer cells from one part of the body (where they first appeared) to another. "Correlation between clinical characteristics and status of CD68, CD163, and SOCS3 in lung metastasis." (PMID 37025997, 2023). "The purpose of our study was to investigate the SOCS3 status in colon primary tumor and lung metastasis and its relationship with macrophages." (PMID 37025997, 2023). "Higher expression of lncRNA DANCR in advanced tumour grades or lymph node metastasis cases promoted the binding of EZH2 to the promoter region of SOCS3 (Suppressor of cytokine-3 signalling) and inhibited SOCS3 expression." (PMID 36685962, 2022).
neutropenia (2 papers, 2012 to 2017). A decrease in the number of neutrophils found in the blood. "A new finding from our study was the association of the SOCS3 rs4969170 polymorphism with HCV treatment-induced neutropenia and thrombocytopenia." (PMID 23133602, 2012). "HCV treatment-induced neutropenia and thrombocytopenia are associated with SOCS3 rs4969170 polymorphism." (PMID 23133602, 2012). "The use of pegIFNα 2a and CD4 cell count ≤350 cells/mL was associated with greater risk of neutropenia while carriers of the SOCS3 rs4969170 AG genotype had significantly lower risk of neutropenia." (PMID 23133602, 2012). "A new finding from our study is the association between HCV treatment-induced neutropenia and thrombocytopenia and the SOCS3 rs4969170 polymorphism." (PMID 23133602, 2012). "In the multivariate analysis, the associations of the SOCS3 gene polymorphism with neutropenia (OR 0.26, 95%CI 0.09–0.75, p = 0.01) and thrombocytopenia (OR 0.07, 95%CI 0.008–0.57, p = 0.01) remained significant." (PMID 23133602, 2012). "Neutropenia and thrombocytopenia are associated with SOCS3 r4969170 polymorphism." (PMID 23133602, 2012). "As Socs3 is a critical negative regulator of granulopoiesis, its level in progenitors of granulocytes can affect the neutrophils differentiation and any significant change may lead to pathological consequences, namely neutrophilia and neutropenia." (PMID 28976973, 2017). "With respect to neutropenia we constructed a multivariate regression model which included the following variables: gender, type of pegIFNα prescribed, CD4 cell count stratified in two categories (≤350 and >350 cells/mL) and SOCS3 rs4969170 genotype." (PMID 23133602, 2012).
nonalcoholic steatohepatitis (2 papers, 2015 to 2022). "An FXR activator blocked nonalcoholic steatohepatitis-dependent HCC progression by suppressing the SOCS3/Jak2/STAT3 pathway." (PMID 35999582, 2022). "In addition, several studies have also demonstrated the important role of Socs3 in the pathogenesis of nonalcoholic steatohepatitis, regulating insulin sensitivity, leptin signaling, glucose metabolism, lipogenesis, and fatty liver." (PMID 25617409, 2015).
pancreatic adenocarcinoma (2 papers, 2022 to 2024). "Furthermore, like SOCS3, it is considered a possible marker of radiosensitivity in pancreatic adenocarcinoma, transcriptionally suppressing the UV radiation resistance-associated gene (UVRAG) and modulating apoptosis, DNA repair, and autophagy." (PMID 39202425, 2024). "Furthermore, survival analysis of these genes was conducted with the Kaplan-Meier method, and as a result, MYLK, SOCS3, STAT5B, and PLAU genes were obtained with the highest mortality rate for pancreatic adenocarcinoma (PAAD) patients." (PMID 35928368, 2022).
pancreatic ductal adenocarcinoma (2 papers, 2022 to 2023). An infiltrating adenocarcinoma that arises from the epithelial cells of the pancreas. "Additionally, it was demonstrated that the suppression of SOCS3 has an impact on progression from pancreatic intraepithelial neoplasia to pancreatic ductal adenocarcinoma." (PMID 35328735, 2022). "In pancreatic ductal adenocarcinoma, HDAC5 could repress the suppressor of cytokine signaling 3 (SOCS3), a negative regulator of chemokine CCL2, contributing to elevated CCL2 and following recruitment of M2 macrophages." (PMID 37273004, 2023).
Parkinson disease (2 papers, 2025). A progressive degenerative disorder of the central nervous system characterized by loss of dopamine producing neurons in the substantia nigra and the presence of Lewy bodies in the substantia nigra and locus coeruleus. "For instance, in Parkinson’s disease (PD), diminished SOCS3 levels could contribute to STAT3 overactivation, potentially worsening microglial activation and neurodegeneration." (PMID 40755762, 2025).
peritonitis (2 papers, 2019 to 2021). Inflammation of the peritoneum (tissue that lines the abdominal wall and covers most of the organs in the abdomen). "Using adoptive transfer of SOCS3-silenced macrophages in a mouse peritonitis model, the investigators demonstrated that SOCS3 drives the production of M1-induced cytokines (TNF-α, IL-1β), while reducing the expression of M2-induced IL-10." (PMID 34339354, 2021).
pleural mesothelioma (2 papers, 2014 to 2018). A neoplasm that arises from the mesothelial cells of the pleura.
pulpitis (2 papers, 2023). Inflammation of the dental pulp. "built a ceRNA network based on differentially expressed data of pulpitis, containing lncRNA PVT1, hsa-miR-455-5p, and 2 mRNAs (SOCS3 and PLXNC1)." (PMID 37275855, 2023). "In the instance of pulpitis, the upregulation of PVT1 promotes inflammation and cytokine and chemokine production, while diminishing the expression of miR-455-5p and indirectly raising the expression of SOCS3 and PLXNC1 and the cytokine cascade." (PMID 36890871, 2023).
renal fibrosis (2 papers, 2013 to 2021). A final common manifestation of a wide variety of chronic kidney diseases characterized by glomerulosclerosis and tubulointerstitial fibrosis. "Therefore, to investigate whether SOCS3 participated in the process of renal fibrosis in UUO rats with macrophage infiltration, SOCS3 protein was detected using immunohistochemistry." (PMID 34630952, 2021). "Examples include upregulation of SOCS3, an inactivator of cytokines, SERPINA3G (Spi-2A) that protects from caspase mediated cell death, NOX2 that may protect against ischemia and oxidative stress and clusterin that protects against renal fibrosis." (PMID 24167575, 2013).
sarcopenia (2 papers, 2011 to 2025). Progressive decline in muscle mass due to aging which results in decreased functional capacity of muscles. "SOCS3, a negative feedback regulator of cytokine signaling, restrains JAK–STAT activation yet is induced by inflammatory cytokines; dysregulated SOCS3 may both reflect and perpetuate elevated cytokine tone implicated in sarcopenia." (PMID 41488001, 2025).
SARS-CoV infection (2 papers, 2021 to 2022). "In vitro studies have shown that SARS-CoV infection can induce the expression of SOCS3, which may be one of the immune escape mechanisms of SARS-CoV-248,49." (PMID 34471088, 2021).